MGMT (O-6-methylguanine-DNA methyltransferase)
Diseases named in the same sentence as MGMT in open-access papers (continued):
Sharing a sentence is not in itself a finding about the gene and the disease.
glioma (continued). "To explore the relationships between the risk signature and clinicopathologic characteristics, we investigated the levels of risk score in different cohorts stratified by glioma grade, age, IDH status, and MGMT promoter status." (PMID 31681595, 2019). "As such, testing for hypermethylated MGMT has entered standard care and management for patients with glioma and is a key factor for treatment strategy selection for GBM patients." (PMID 31803237, 2019). "In glioma patients, the co-occurrent hypermethylation of KEAP1 and MGMT predicts a lower risk of progression for patients treated with radiotherapy and temozolomide." (PMID 31159323, 2019). "This review describes the regulation of MGMT expression and its role in chemotherapy, especially in glioma." (PMID 32010632, 2019). "MGMT methylation constitutes a well-known predictive biomarker of gliomas used to infer which patients would have a better response to chemotherapy with temozolomide." (PMID 31623593, 2019). "18F-FDG-PET-based radiomics is a promising approach for preoperatively evaluating the MGMT promoter methylation status in glioma and predicting the prognosis of glioma patients noninvasively." (PMID 31426864, 2019). "Promoter methylation-induced O6-methylguanine DNA methyltransferase (MGMT) inactivation improves the efficacy of alkylating agents in gliomas, colorectal cancer and diffuse large B cell lymphoma." (PMID 30616628, 2019). "The recently reported RTOG 0424 trial also suggests that the MGMT promotor methylation status can predict the prognosis of patients with low-grade glioma treated with radiotherapy and TMZ." (PMID 31426864, 2019). "Some molecular genetic features including IDH1/2 mutation, MGMT promoter methylation, co-deletion of 1p/19q, TERT loss, and ATRX mutation have been reported to be associated with favorable prognosis in gliomas." (PMID 30658672, 2019). "MGMT promoter methylation and its protein levels are known to determine the sensitivity of gliomas to TMZ." (PMID 31652645, 2019). "There are clear indications that the MGMT promoter methylation can change from the primary tumor to relapse in about 24% of glioma patients." (PMID 31766430, 2019). "To further explore its clinical application, we investigated the relationship between the risk score and glioma subtype, IDH1 and MGMT promoter status, respectively." (PMID 31379707, 2019). "In contrast, the inhibition of NF-κB by the small molecule inhibitor BAY 11-7082 or by siRNA-mediated gene silencing reduced MGMT levels and thereby sensitized glioma stem-like cells to TMZ treatment." (PMID 31906036, 2019). "The expression of MGMT was also regulated by histone methylation and acetylation in many cancer models, including gliomas." (PMID 30542120, 2019). "A similar screen of the Web of Science database was carried out, but did not yield additional reports of sufficient quality on our topic of MGMT methylation changes in gliomas." (PMID 31766430, 2019). "The objective of this study is to investigate the clinical utility of serum O‐6‐methylguanine‐DNA methyltransferase (MGMT) autoantibodies as novel biomarkers for prediction of recurrence and treatment response for glioma through MGMT peptides microarray." (PMID 31210005, 2019). "Monitoring of anti‐MGMT‐02 peptide autoantibody levels was useful for identifying patients with glioma recurrence from preoperative seropositive patients." (PMID 31210005, 2019). "This study aimed to build a radiomics signature based on 18F-fluorodeoxyglucose (FDG) positron emission tomography (PET) for noninvasive measurement of the MGMT promoter methylation status in glioma." (PMID 31426864, 2019). "Autoantibodies to MGMT peptides were detected in sera from glioma patients and five highly responsive autoantibodies to peptides were identified in the glioma group." (PMID 31210005, 2019).
glioma (continued). "By Kaplan Meir (KM) analysis, OS and PFS of glioma patients were compared to both MGMT promoter methylation status and its protein expression by multivariate analyses." (PMID 29712977, 2018). "Primary glioma cells were incubated with an MGMT substrate, either O6BG or PAM-OBG, for a defined time period and then 100 μM O6PGG was added, and 10 minutes later the cells were fixed with paraformaldehyde (PFA)." (PMID 29844863, 2018). "To establish this model, we transfected GL261 murine glioma cells with a plasmid that carries the murine MGMT gene under a mouse medium-strength promoter (i.e., the murine phosphoglycerate kinase 1 promoter)." (PMID 30413113, 2018). "The results show that the transcript levels of PTPN2 were decreased in gliomas with MGMT promoter methylation in both CGGA (p = 0.013) and TCGA (p < 0.001) datasets." (PMID 29764444, 2018). "High level of DNA repair protein, O6-methylguanine-DNA-methyltransferase (MGMT) and occurrence of glioma stem-like cells contribute to GBM resistance to the drug." (PMID 30450051, 2018). "A relatively small variability of MGMT expression within a given pituitary adenoma has been attributed to the homogeneous population of adenoma cells in contrast to more heterogeneous glioma cells." (PMID 29344904, 2018). "MGMT, an enzyme involved in DNA repair, plays a significant role in the resistance of glioma tumors to temozolomide." (PMID 30583528, 2018). "Another potential method was to sensitize glioma cells to TMZ by concomitant use of the MGMT pseudosubstrate." (PMID 29761922, 2018). "The U-118 glioma cell line, in which the MGMT gene is hypermethylated, is more sensitive to TMZ when the PI3K/AKT/mTOR and ERK/MAPK signaling pathways are inhibited." (PMID 30486451, 2018). "MGMT was identified as an important biomarker capable of predicting the sensitivity of glioma patients to TMZ treatment." (PMID 29487691, 2018). "Though in sync with our report that MGMT methylation favors longer survival in glioma patients treated with TMZ therapy but notably survival was longer in our series of patients." (PMID 29712977, 2018). "Expression of genes involved in the immune response was positively related to glioma grades but negatively associated with IDH1 mutation and MGMT promoter methylation." (PMID 29764444, 2018). "In human gliomas, the expression of MGMT proteins has been detected and regarded as a prognostic factor." (PMID 29301329, 2018). "Our results demonstrate that [Ca2+]i-dependent glycogenolysis is required for TMZ resistance, stimulated by both the transactivation of Na,K-ATPase/ERK1/2 and the upregulation of MGMT expression in glioma cells." (PMID 30131700, 2018). "The relationship between PAM-OBG concentration, incubation time, and levels of active MGMT was explored by titrating glioma with PAM-OBG for 0.5, 1 and 2 hours, prior to addition of O6PGG." (PMID 29844863, 2018). "Glioma-associated DEGs DOCK6, ILK, MGMT, NOTCH4 were up-regulated and FGF10, JAK1, JUNB, RHOB were down-regulated uniquely in the mouse." (PMID 29352201, 2018). "It shows that in a large subgroup of patients, MGMT gene with methylated sequences unambiguously serves as the genetic fingerprint with highest clinical impact on outcome of the glioma patients when treated with Temozolomide and radiotherapy." (PMID 29712977, 2018). "In glioma, resistance to drugs such as temozolomide are mediated through the DNA repair protein O6-methylguanine-DNA methyltransferase (MGMT)." (PMID 29301334, 2018). "Both MGMT parameters proved to be significant prognostic factors in our series of glioma cases across different histological types of glioma." (PMID 29712977, 2018). "Contrarily, MGMT removes alkylating adducts from the O6 position of guanine and thus protects glioma cells from this cytotoxicity." (PMID 30583528, 2018). "Of the 63 glioma samples analyzed for pattern of methylation, 38 (60.3%) cases showed methylation in MGMT gene and 22 (39.7%) were unmethylated." (PMID 29712977, 2018).
glioma (continued). "PAM-OBG ablates glioma MGMT in mouse intracranial models, potentiating TMZ chemoradiation, however, PAM-OBG does not itself potentiate radiotherapy." (PMID 29844863, 2018). "Paradoxically, the higher MGMT content in gliomas serves to remove the mutagenic and cytotoxic O6-alkylguanines and confer tumor drug resistance and therapy failure." (PMID 29423059, 2018). "We conclude both parameters of MGMT should be confirmed to benefit the glioma patients while deciding for chemotherapy with Temozolomide to manage the disease efficiently." (PMID 29712977, 2018). "We first derived a TMZ-resistant population of murine glioma cells after transfecting the GL261 cells with a plasmid construct carrying MGMT placed under the control of a medium-strength mouse promoter." (PMID 30413113, 2018). "Many glioma cells develop drug-resistance against TMZ that is mediated by increasing O-6-methylguanine-DNA methyltransferase (MGMT) levels." (PMID 29301329, 2018). "This aided us in further fitting the data for the refinement of predictive power of MGMT gene parameters in Glioma patients and their treatment outcome." (PMID 29712977, 2018). "The resulting CpG Island Methylator Phenotype (CIMP) accounts for major gene expression changes including the silencing of the MGMT (O6-methylguanine DNA methyltransferase) repair protein in gliomas." (PMID 29439493, 2018). "Factors including age at diagnosis, WHO Grade, ADAR3 expression, MGMT promoter methylation, IDH1/2 mutation status and radiotherapy were significantly associated with the OS of glioma patients." (PMID 30524204, 2018). "Sixty three cases of glioma were evaluated for MGMT promoter methylation by methylation-specific PCR (MS-PCR) and protein expression by immunostaining (IHC)." (PMID 29712977, 2018). "The experiments were performed using human U251 and LN18 glioma cell lines with different status of the MGMT gene promoter." (PMID 30450051, 2018). "Conversely, glioma patients with high expression of MGMT, and reduced MGMT methylation, had a poor response to TMZ." (PMID 30131700, 2018). "To confirm MEGF10 as an independent predictor with previous widely accepted factors (age, WHO histological grade, and MGMT promoter status), we collected and analyzed the corresponding clinical and molecular information of glioma patients from TCGA datasets." (PMID 29887919, 2018). "There is a growing evidence that molecular markers such as IDH1/2 mutations, MGMT promoter methylation, TERT promoter mutational status or 1p/19q co-deletion are important for diagnosis and prognosis of glioma patients." (PMID 29535343, 2018). "We have designed and tested both in vitro and in vivo, a monoamine oxidase B (MAOB) specific prodrug, PAM-OBG, that is converted by glioma MAOB into the MGMT inhibitor O6-benzylguanine (O6BG) and the DNA crosslinking agent acrolein." (PMID 29844863, 2018). "Nearly all IDH1-mutant gliomas contain methylated O-6-methylguanine-DNA methyltransferase (MGMT) genes, which sensitize tumors to temozolomide (TMZ) therapy." (PMID 29643764, 2018). "In the present study, we show that XIST/miR-29c coregulates SP1 and MGMT expression in TMZ-resistant glioma cell lines." (PMID 28831025, 2017). "The median methylation level of MGMT was significantly higher in glioma patients 64.65% (IQR, 54.87%–74.37%) compared to 38.30% (IQR, 34.13%–45.45%) in healthy controls (P<0.01)." (PMID 29100349, 2017). "The median methylation level of MGMT in glioma samples was 64.65% (IQR, 54.87%–74.37%) compared to 38.30% (IQR, 34.13%–45.45%) in healthy controls, and all revealed significant differences including P16." (PMID 29100349, 2017). "After TMZ treatment, aggressive glioma cells acquire resistance in MGMT-dependent and -independent pathways." (PMID 28530704, 2017). "For instance, O6-methylguanine DNA methyltransferase (MGMT) methylation is a useful predictor of the responsiveness of tumors to alkylating agents, and survival of patients with glioma." (PMID 28881822, 2017).
glioma (continued). "NF-κB plays an important role in regulation of MGMT activity in glioma cells by activating MGMT gene expression through two NF-κB binding sites within the MGMT promoter." (PMID 28598356, 2017). "In order to explore the relationship between serum cell-free DNA aberrant methylation and survival of glioma patients, we compared the methylation level of Alu, MGMT in different glioma grade groups and constructed the survival curves." (PMID 29100349, 2017). "The methylation of the promoter region of MGMT gene suppresses MGMT expression, resulting in an improvement in the prognosis of glioma patients." (PMID 29062386, 2017). "This is also true for all other gliomas or other tumors where MGMT promoter methylation allows alkylating chemotherapies to be effective." (PMID 28367251, 2017). "We analyzed the relevance between rs16906252 polymorphisms, the MGMT methylation status, and the OST in 72 Han-Chinese gliomas patients." (PMID 28575062, 2017). "Expression of MGMT was verified in multiple cancer cell types and three MGMT-expressing solid tumor cell lines (T98G glioma, and H460 and A549 NSCLC) were selected for further experiments." (PMID 28752860, 2017). "Our findings provide a novel understanding of the function of XIST/miR-29c/SP1/MGMT in the sensitivity of glioma to chemotherapy and the mechanism involved." (PMID 28831025, 2017). "Taken together, these data suggest that XIST can inhibit miR-29c expression by directly binding to miR-29c and subsequently up-regulate the expression of SP1 and MGMT to promote the chemoresistance of glioma cells to TMZ." (PMID 28831025, 2017). "Promoter methylation of O-6-methylguanine-DNA methyltransferase (MGMT) is an important clinical predictor to overall survival time (OST) in gliomas and other cancers including colorectal cancer, lymphoma and lung cancer." (PMID 28575062, 2017). "Some molecular genetic features including IDH1/2 mutation, MGMT promotor methylation, codeletion of 1p/19q, TERT loss, and ATRX mutation have been reported to be associated with favorable prognosis in gliomas." (PMID 29110682, 2017). "Two senior pathologists evaluated each slide for determining histology grades (I, II, III and IV) and glioma parameters, such as Ki-67 index, MGMT expression and tumor latency." (PMID 28710382, 2017). "High BICD1 expression also showed more significant impact (P=0.009932) than high MGMT expression (P=0.028420) on worse overall survival in the CGGA (Chinese Glioma Genome Atlas) cohort." (PMID 29371945, 2017). "Our results indicated that miR-29c indirectly suppressed MGMT expression by targeting Sp1 in glioma cells." (PMID 27384876, 2016). "Strategies aiming at reducing chemoresistance by compromising the MGMT enzyme are therefore highly relevant for migrating glioma cells and new drugs added to temozolomide should also reach these tumor cells to be efficient." (PMID 27171431, 2016). "In this study, based on our previously reported group of 139 glioma patients, we randomly selected 90 patients for further evaluation of MGMT promoter methylation." (PMID 27834917, 2016). "Patients whose gliomas, even high-grade gliomas, have methylation of the promoter region of the gene for MGMT (which thereby suppresses expression of this DNA repair enzyme) have better response to radiation and alkylator chemotherapy and have longer survival." (PMID 27242937, 2016). "This suggests that blocking the Hh pathway enhances the cytotoxicity of TMZ in glioma cells by downregulating the expression of MGMT." (PMID 27894350, 2016).
glioma (continued). "MGMT is frequently methylated in various tumors, including gliomas (40%), diffuse large B-cell lymphoma (36%), colorectal cancer (46%), gastric cancer (36.8%), non-small cell lung cancer (21%), esophageal cancer (44%) and head and neck cancers (60.8%)." (PMID 26967246, 2016). "In silico analyses of The Cancer Genome Atlas (TCGA) and Chinese Glioma Genome Atlas (CGGA) revealed that miR-181d-5p is the only miRNA that consistently exhibited inverse correlation with MGMT mRNA expression." (PMID 27057640, 2016). "MGMT-mediated removal of alkyl groups from O6-MG is also relevant in alkylating chemotherapy with temozolomide and nitrosourea derivatives of gliomas, the most common malignant tumor of the brain." (PMID 27057640, 2016). "The association between MGMT promoter methylation and clinical outcome (using a 5 % cut-off value) comparing HRM, MSP, and PSQ was analyzed in tumor material of 65 IDH1 wt glioma patients (seven gliomas grade III and 58 grade IV)." (PMID 27158275, 2016). "Early clinical studies showed that glioma patients with methylated MGMT promoters had a survival benefit treated with radiotherapy." (PMID 27057637, 2016). "Since MGMT is highly epigenetically regulated, the MGMT promoter methylation status is taken as an indicator of MGMT silencing, predicting the outcome of glioma therapy." (PMID 27158275, 2016). "The percentage of tumors with methylated MGMT-Promotor (4/17 = 24%), which is considered as an important prognostic marker in high-grade gliomas, corresponds with the finding of other studies." (PMID 26978262, 2016). "While, silencing MGMT by promoter region hypermethylation sensitizes glioma cells to alkylating agents." (PMID 26967246, 2016). "In gliomas, enhanced sensitivity to alkylating agents was initially suggested in the subgroup of patients with reduced MGMT activity." (PMID 26967246, 2016). "Glioma cells treated with TMZ exhibited significant increases in MGMT, Notch1 and Hes1 mRNA, and protein levels." (PMID 27894350, 2016). "3D-cultured cells also exhibited enhanced resistance to chemotherapeutic alkylating agents, with a much higher proportion of glioma stem cells and upregulation of O6-methylguanine DNA methyltransferase (MGMT)." (PMID 27486877, 2016). "It is superior in predicting PFS and OS of high-grade glioma patients compared to MSP and, therefore, can be recommended being used routinely for determination of the MGMT status of gliomas." (PMID 27158275, 2016). "Consistent with clinical results, we found that MGMT was upregulated in glioma cells in 3D collagen scaffold cultures." (PMID 27486877, 2016). "High MGMT activity in glioma promotes resistance to alkylating agent chemotherapeutics, as shown by increased resistance of our 3D-cultured glioma cells to CCNU and TMZ." (PMID 27486877, 2016). "MGMT methylation is a marker for poor prognosis in human glioma, while, MGMT methylation is a sensitive marker of glioma cells to alkylating agents." (PMID 26967246, 2016). "In order to further analyse the correlation between miR-370-3p and MGMT expression in glioma cancer tissue, our study examined miR-370-3p and mRNA of MGMT in all glioma and their correspondingly matched normal adjacent tissues." (PMID 27595933, 2016). "In another study, sensitization of glioma cells to TMZ by JNK inhibitors was observed in MGMT expressing cells due to an impact of JNK on the basal expression of this DNA repair gene." (PMID 26418950, 2015). "Modulation of tumor vasculature, down-regulation of MGMT expression and induction of apoptosis by IFN-β independently of MGMT-mediated resistance to temozolomide have been discussed as mechanisms of this anti-glioma effect." (PMID 26441059, 2015). "Methylation of MGMT promoter is found in 40% of cancer types such as glioma and colorectal cancer and in 25% of non-small cell lung carcinoma, lymphoma and head and neck carcinoma." (PMID 26035292, 2015).